SLC7A1 (solute carrier family 7 member 1)
Description:
High-affinity, low capacity permease involved in the transport of the cationic amino acids (arginine, lysine and ornithine) in non-hepatic tissues.
Synonyms: CAT-1; ATRC1; ERR; REC1L; HCAT1
Tractability: Antibody: its Gene Ontology location is reachable by antibodies, with high confidence; UniProt places it where antibodies can reach, with medium confidence; UniProt predicts a signal peptide or a membrane-spanning region. PROTAC: ubiquitination databases record sites on it; its protein half-life has been measured.
Gene: Protein-coding gene on chromosome 13 (29,509,410 to 29,595,781, reverse strand). Ensembl gene ENSG00000139514.
Subcellular location: Cell membrane
Pathways (Reactome):
Transport of small molecules: Amino acid transport across the plasma membrane
Gene Ontology:
Molecular function: amino acid transmembrane transporter activity; basic amino acid transmembrane transporter activity; L-arginine transmembrane transporter activity; L-histidine transmembrane transporter activity; L-lysine transmembrane transporter activity; protein binding; L-ornithine transmembrane transporter activity; transmembrane transporter activity; virus receptor activity
Biological process: amino acid import across plasma membrane; L-amino acid transport; L-arginine transmembrane transport; L-histidine import across plasma membrane; L-lysine transmembrane transport; lysine transport; ornithine transport; positive regulation of T cell proliferation; amino acid transport; L-arginine import across plasma membrane; L-ornithine transmembrane transport; monoatomic cation transmembrane transport; transport across blood-brain barrier; symbiont entry into host cell; transmembrane transport
Cellular component: apical plasma membrane; basolateral plasma membrane; membrane; plasma membrane; protein-containing complex; basal plasma membrane
Genetic constraint (gnomAD): Loss-of-function variants: 11 observed, 51.62 expected, observed/expected ratio (o/e) 0.21, 90% interval 0.13 to 0.35. The upper end of that interval is the gene's LOEUF score, 0.35, which puts it in group 1 of 6, group 1 being the genes least tolerant of losing a copy. Missense variants: 495 observed, 803.01 expected, observed/expected ratio (o/e) 0.62, 90% interval 0.57 to 0.66. Synonymous variants: 326 observed, 332.5 expected, observed/expected ratio (o/e) 0.98, 90% interval 0.89 to 1.08.
Homologues: Orthologues: chimpanzee SLC7A1 (99% identical), macaque SLC7A1 (99% identical), dog SLC7A1 (92% identical), pig SLC7A1 (91% identical), rabbit SLC7A1 (90% identical), guinea pig SLC7A1 (88% identical), rat Slc7a1 (88% identical), mouse Slc7a1 (87% identical), zebrafish SLC7A1 (72% identical), tropical clawed frog slc7a1 (71% identical), zebrafish slc7a1a (70% identical), Drosophila melanogaster CG7255 (45% identical), and 10 more. Paralogues in human: SLC7A2 (60% identical), SLC7A3 (58% identical), SLC7A14 (44% identical), SLC7A4 (40% identical), SLC7A6 (20% identical), SLC7A8 (20% identical), SLC7A7 (19% identical), SLC7A11 (19% identical), SLC7A10 (18% identical), SLC7A5 (18% identical), SLC7A9 (17% identical), SLC7A13 (16% identical).
Diseases named in the same sentence as SLC7A1 in open-access papers:
SLC7A1 is named in the same sentence as 53 diseases in open-access papers, as found by Europe PMC text mining. Sharing a sentence is not in itself a finding about the gene and the disease. The quoted sentences say what the papers report.
breast carcinoma (11 papers, 2017 to 2025). "In human breast cancer cells, colorectal cancer, and ovarian cancer cells, overexpression of SLC7A1 is beneficial to the growth and survival of tumor cells, and promotes the malignant progression of tumors." (PMID 38752472, 2024). "The amplified expression of lysosomal arginine transporter SLC7A1 is frequently found in various solid tumors, including hepatocarcinoma, colorectal cancer, breast cancer, and ovarian cancer." (PMID 38247807, 2024). "Like the previous study, SLC7A1 is involved in L-(2,3,4,5-H3)-arginine uptake, and its silencing of SLC7A1 was proved to result in apoptosis induction in breast cancer cells." (PMID 38705513, 2024). "Current studies have shown that SLC7A1 is involved in tumor progression in liver, colorectal, and breast cancer." (PMID 36131790, 2022). "This revealed numerous genes whose expression was altered by reducing YB-1, including several related to hypoxia (e.g., PPIF, SLC3A2 and SLC7A1) and found to be elevated in breast cancers with increased expression or amplification of YB-1." (PMID 34294889, 2022). "Modulation of SLC7A1 expression in colorectal carcinoma and breast cancer cells decreases arginine uptake and reduces their proliferation and survival." (PMID 28969007, 2017). "Also, together with prolactin (PRL) and 17β-estradiol (E2), SLC7A1 induces nitric oxide synthase to produce NO, thereby increasing breast cancer cell survival." (PMID 38705513, 2024). "The increased expression of SLC7A1 and SLC7A2 is associated with a poor prognosis of breast cancer." (PMID 39852119, 2024). "SLC7A1 gene expression in the human breast cancer cell lines McF-7 and T47D has been found to be higher than that in normal breast cell lines, and apoptosis of McF-7 and T47D cells was significantly increased after SLC7A1 gene knockdown." (PMID 36131790, 2022). "The transporters SLC1A1, SLC7A1, and SLC7A11 are highly expressed in luminal subtypes of breast cancer and TNBC." (PMID 39852119, 2024). "Modulation of SLC7A1 expression via siRNA-mediated knockdown results in cell growth inhibition in CRC and breast cancer cells." (PMID 37749499, 2023). "In high L-arginine-dependent tumors, such as breast cancer, CRC, and HCC, increased expression of the transporter CAT-1 (SLC7A1) has been observed, and CAT-1 (SLC7A1) knockdown decreases the viability of cancer cells and induces apoptosis." (PMID 33511116, 2020). "In our comprehensive literature search through PubMed, we found eight amino acid transporters from SLC7A1 to SLC7A14 have not been studied in breast cancer." (PMID 38204267, 2025). "In addition to breast cancer cells, increased levels of l-arginine in CRC cells by SLC7A1 also resulted in tumor cell growth." (PMID 38705513, 2024). "Also, in TNBC and luminal breast cancer subtypes, but not in those with positive HER2 expression, the adjacent expression of SLC7A1 and SLC7A11 is observed." (PMID 39852119, 2024).
colorectal cancer (7 papers, 2017 to 2024). A primary or metastatic malignant neoplasm that affects the colon or rectum. "More importantly, a monoclonal anti SLC7A1 antibody inhibited the in vivo growth of human colorectal carcinoma tumors in nude mice." (PMID 37749499, 2023). "SLC7A1 mRNA and protein levels have been found to be higher in colorectal cancer (CRC) tissues than in normal tissues, and the application of an anti-SLC7A1 monoclonal antibody in colorectal cancer cell lines showed prominent antitumor activity." (PMID 36131790, 2022). "Similarly, the SLC7A1/CAT1 arginine transporter plays a critical function in colorectal cancer by increasing arginine metabolism." (PMID 35884586, 2022).
essential hypertension (5 papers, 2013 to 2020). Hypertension that presents without an identifiable cause. "Another study has identified a correlation between a novel polymorphism on the solute carrier family 7 member 1 (SLC7A1) gene and the onset of essential hypertension." (PMID 28660188, 2017). "A polymorphism in the 3′-UTR of SLC7A1 was found to be associated with hypertension and endothelial dysfunction, probably due to the binding of miR-122 to the region." (PMID 24805109, 2014). "Gene variation rs41318021 in the human SLC7A1, which encodes the principal arginine transporter, has previously been proposed to associate with a genetic predisposition to essential hypertension." (PMID 23841815, 2013). "Therefore, changes in SLC7A1 gene could cause dysfunction of endothelium and lead to hypertension." (PMID 23841815, 2013). "When SLC7A1 functionality, and thus arginine transport, is lost, nitric oxide production can become abnormal, potentially resulting in certain vascular disorders, such as hypertension." (PMID 31146342, 2019). "Coupled together, these results and our outcomes suggest that mRNA expression levels of SLC7A1 may serve as both a tissue and blood biomarker of hypertension in workers exposed to MWCNTs and may be particularly useful in workers with preexisting cardiovascular disease." (PMID 31146342, 2019).
glioma (4 papers, 2015 to 2024). A benign or malignant brain and spinal cord tumor that arises from glial cells (astrocytes, oligodendrocytes, ependymal cells). "Particularly, ECs from glioma exclusively expressed a series of transmembrane transport-associated genes, including SLC2A1, BSG, SLC7A1, and SLC7A5, suggesting that ECs in brain tumors were still involved in retaining the brain-blood barrier." (PMID 39345334, 2024). "However, other transcription factor(s) that reduce SLC7A1 transcriptional activity, such as the C/EBP homologous protein 10 (CHOP) as reported in C6 rat glioma cells, may be involved in mediating insulin effects." (PMID 25875935, 2015).
hepatocellular carcinoma (4 papers, 2022 to 2025). A malignant tumor that arises from hepatocytes. "SLC7A1 overexpression has been reported in several cancers, including colorectal tumors and hepatocellular carcinoma." (PMID 37749499, 2023). "SLC7A1 has been widely studied in hepatocellular carcinoma (HCC)." (PMID 36131790, 2022). "In hepatocellular carcinoma (HCC), SLC7A1 specifically introduces arginine, and its inhibition slows the growth of HCC cells in vivo and in vitro." (PMID 38752472, 2024).
ovarian carcinoma (4 papers, 2022 to 2024). A malignant neoplasm originating from the surface ovarian epithelium. "In this manuscript, transwell coculture experiments were used to find that CAFs regulated the migration and invasion ability of ovarian cancer cells through SLC7A1." (PMID 38752472, 2024). "Compared with normal ovarian cells and normal fibroblasts, the expression of SLC7A1 in ovarian cancer cell lines and CAF was enhanced." (PMID 38752472, 2024). "In ovarian cancer, an elevated expression of the arginine transporter SLC7A1 in tumor tissue is known to be correlated with a poor survival outcome for patients." (PMID 38247807, 2024). "We also found that high expression of SLC7A1 in ovarian cancer triggers downstream MAPK and EMT pathways." (PMID 38752472, 2024). "In general, in HGSOC, CAFs overexpressing SLC7A1 supported the migration and invasion of tumor cells; SLC7A1 is highly expressed in ovarian cancer and is involved in ERK phosphorylation and EMT signaling in MAPK signaling pathway." (PMID 38752472, 2024). "In this study, the sequence variation of SLC7A1 in ovarian cancer accounted for 0.9% of the total sample." (PMID 36131790, 2022). "We performed in vitro experiments to identify the expression and biological function of SLC7A1 in epithelial ovarian cancer (EOC) tissues and cells." (PMID 36131790, 2022). "As a protein highly expressed in OC, we found that SLC7A1 was positively correlated with CD4+ resting memory cells, CD8+ effector memory cells, cancer-associated fibroblasts (CAFs), and M0 macrophages in ovarian cancer by immune evaluation (P < 0.05)." (PMID 36131790, 2022). "We used bioinformatics analysis to explore SLC7A1 expression level, prognostic value, and tumor mutation burden (TMB) in ovarian cancer (OC) tissues." (PMID 36131790, 2022). "In this manuscript, we further found that SLC7A1 overexpression in ovarian cancer cells triggers the MAPK signaling pathway downstream of cancer cells, and expanded the significance and mechanism of SLC7A1 expression in stromal tumor‐associated fibroblasts (CAFs) of HGSOC." (PMID 38752472, 2024). "Most current studies on SLC7A1 have focused on tumor cells, and our previous studies have discussed that high expression of SLC7A1 in ovarian cancer tumor cells promotes tumor malignant progression, is involved in cancer cell amino acid metabolism, and is associated with poor PFS." (PMID 38752472, 2024). "As more and more tumor mutation loads are being found in CAFs, SLC7A1 is not the only gene driving ovarian cancer metastasis, as metastasis is a multisignaling, multistep complex process involving the interaction of multiple components in the tumor microenvironment." (PMID 38752472, 2024). "Therefore, SLC7A1 is a promising target for ovarian cancer treatment." (PMID 36131790, 2022). "Therefore, amplification may be one of the main mechanisms of SLC7A1 overexpression in ovarian cancer." (PMID 36131790, 2022). "The effect of SLC7A1 on MAPK and EMT pathway proteins in ovarian cancer (OC) was verified by RNA sequencing and western blotting." (PMID 38752472, 2024). "The uptake and transport of arginine across cell membranes are mediated by cationic amino acid transporters, specifically SLC7A1/CAT1, which are highly expressed in ovarian cancer and are involved in the metabolic reprogramming of arginine, ultimately promoting platinum resistance." (PMID 37681030, 2023). "Our previous studies have shown that upregulation of SLC7A1 in epithelial ovarian cancer (EOC) tumor cells significantly increases cancer cell proliferation, migration, and cisplatin resistance; however, the molecular mechanism by which SLC7A1 functions in EOC remains unknown." (PMID 38752472, 2024).
prostate carcinoma (3 papers, 2018 to 2025). A carcinoma that arises from epithelial cells of the prostate gland. "After constructing the prognostic prediction model, SLPI, VSIG2, CENPF, SLC7A1, SMC4, and ITPR2 were finally regarded as the key genes in the prognosis of patients with prostate cancer." (PMID 36937411, 2023).
brain tumors (2 papers, 2017 to 2024). "Here we show in large in silico patient cohorts that paediatric sarcomas and brain tumours express predominately the arginine transporter SLC7A1 and the arginine metabolising enzyme Arginase 2 (ARG2), but have low-absent expression of OTC." (PMID 28969007, 2017).
endothelial dysfunction (2 papers, 2014 to 2020). In vascular diseases, endothelial dysfunction is a systemic pathological state of the endothelium (the inner lining of blood vessels) and can be broadly defined as an imbalance between vasodilating and vasoconstricting substances produced by (or acting on) the endothelium. "In hypertensive patients, lower levels of nitric oxide (NO), linked with endothelial dysfunction, have been associated with miR-122, which binds the 3′UTR of SLC7A1 and induces the reduction of SLC7A1 levels." (PMID 33375647, 2020).
hepatoblastoma (2 papers, 2023 to 2024). Hepatoblastoma (HB) is a malignant hepatic tumor and is the most common pediatric liver cancer. "In hepatoblastoma (HB), SLC7A1, acting as a substrate of the tumor suppressor gene SPOP, modulates the progression of HB through the regulation of arginine metabolism, thereby offering a novel therapeutic target for HB." (PMID 38903179, 2024). "SLC7A1 (solute carrier family 7 member 1), for example, could be a SPOP substrate and influence cell phenotypic via regulating arginine metabolism, as well as regulate the hepatoblastoma process." (PMID 37337170, 2023).
liver cancer (2 papers, 2021 to 2024). An epithelial or non-epithelial malignant neoplasm that arises from the liver. "Recent investigations have demonstrated the association of SLC7A1 with tumor development in breast, epithelial ovarian and liver cancer." (PMID 38903179, 2024).
meningioma (2 papers, 2023 to 2025). A generally slow growing tumor attached to the dura mater. "Here, we revealed that SLC7A1 was upregulated in high-grade meningioma, and high SLC7A1 expression was associated with poor prognosis of meningioma patients." (PMID 41184266, 2025). "SLC7A1 was highly expressed in high-grade meningioma and associated with poor prognosis of patients." (PMID 41184266, 2025). "As a cationic amino acid transporter, SLC7A1 was highly expressed in high-grade meningioma and associated with poor prognosis of patients." (PMID 41184266, 2025). "RNA sequencing analysis revealed a significant decrease in the transcriptional activity of FOXM1 and E2F4 in IOMM-Lee and SZ8511 meningioma cells following SLC7A1 knockdown." (PMID 41184266, 2025). "To assess the effect of SLC7A1 on meningioma cells, we knocked down the expression of SLC7A1 with siRNA in vitro." (PMID 41184266, 2025). "AZ628, predicted as a small molecule drug targeting high-SLC7A1 meningiomas, exhibited an excellent antitumor effect against meningioma in vitro, in vivo, and in organoid models." (PMID 41184266, 2025). "CCK-8 and clone formation assays showed that the proliferation of meningioma cells was significantly inhibited by SLC7A1 knockdown." (PMID 41184266, 2025). "In vitro and in vivo experiments demonstrated that knockdown of SLC7A1 significantly inhibited the proliferation, invasion, and xenograft tumor growth of meningioma cells." (PMID 41184266, 2025). "Although several studies have demonstrated the oncogenic role of SLC7A1 in various cancers, the downstream pathways and molecular targets regulated by SLC7A1 remain largely unclear, and its function in meningioma is yet to be elucidated." (PMID 41184266, 2025). "Knockdown of SLC7A1 significantly inhibited the proliferation, invasion, and xenograft tumor growth of meningioma cells." (PMID 41184266, 2025). "To uncover the transcription factors regulated by SLC7A1 in meningioma cells, we conducted transcription factor activity scoring analysis, referencing the previously reported methods." (PMID 41184266, 2025). "To gain deeper insights into the molecular functions of SLC7A1 in meningioma, we conducted mRNA sequencing on meningioma cells IOMM-Lee and SZ8511 after knocking down the expression of SLC7A1." (PMID 41184266, 2025). "Spearman’s correlation analysis revealed that SLC7A1 expression was positively correlated with ki67 index in meningioma (r = 0.404, P < 0.001)." (PMID 41184266, 2025). "The result showed that knockdown of SLC7A1 significantly inhibited meningioma growth in vivo, further confirming the essential role of SLC7A1 in meningioma." (PMID 41184266, 2025). "The Genomics of Drug Sensitivity in Cancer (GDSC) database was utilized for predicting potential drugs targeting high-SLC7A1 meningiomas." (PMID 41184266, 2025). "AZ628 and PD-0325901 were the top two drugs with the highest sensitivity to high-SLC7A1 meningiomas." (PMID 41184266, 2025). "In brief, our study demonstrated the tumor-promoting function of SLC7A1 by regulating the transcription factors FOXM1 and E2F4 in meningioma and identified SLC7A1 as a potential therapeutic target." (PMID 41184266, 2025). "Kaplan-Meier analysis showed that meningioma patients with SLC7A1 expression >4 TPM experienced a worse prognosis than those with SLC7A1 expression <4 TPM (HR = 2.663, P = 0.0341)." (PMID 41184266, 2025). "As an arginine transporter, SLC7A1 showed significant correlation with malignant phenotypes in meningioma both at the single-cell level and bulk level." (PMID 41184266, 2025). "In conclusion, targeting SLC7A1 emerges as a promising strategy for the treatment of high-grade meningioma." (PMID 41184266, 2025). "Although several studies have suggested the oncogenic role of SLC7A1 in various tumors, the downstream pathways and molecular targets regulated by SLC7A1, as well as its functional role in meningioma, remain largely unexplored." (PMID 41184266, 2025).